IL2 (interleukin 2)
Description:
Cytokine produced by activated CD4-positive helper T-cells and to a lesser extend activated CD8-positive T-cells and natural killer (NK) cells that plays pivotal roles in the immune response and tolerance. Binds to a receptor complex composed of either the high-affinity trimeric IL-2R (IL2RA/CD25, IL2RB/CD122 and IL2RG/CD132) or the low-affinity dimeric IL-2R (IL2RB and IL2RG). Interaction with the receptor leads to oligomerization and conformation changes in the IL-2R subunits resulting in downstream signaling starting with phosphorylation of JAK1 and JAK3. In turn, JAK1 and JAK3 phosphorylate the receptor to form a docking site leading to the phosphorylation of several substrates including STAT5. This process leads to activation of several pathways including STAT, phosphoinositide-3-kinase/PI3K and mitogen-activated protein kinase/MAPK pathways. Functions as a T-cell growth factor and can increase NK-cell cytolytic activity as well. Promotes strong proliferation of activated B-cells and subsequently immunoglobulin production. Plays a pivotal role in regulating the adaptive immune system by controlling the survival and proliferation of regulatory T-cells, which are required for the maintenance of immune tolerance. Moreover, participates in the differentiation and homeostasis of effector T-cell subsets, including Th1, Th2, Th17 as well as memory CD8-positive T-cells.
Synonyms: IL-2; TCGF; lymphokine
Tractability: Small molecule: a structure with a bound ligand is known; a high-quality ligand is known; it has a binding pocket of medium quality. Antibody: its Gene Ontology location is reachable by antibodies, with high confidence; UniProt places it where antibodies can reach, with medium confidence; UniProt predicts a signal peptide or a membrane-spanning region. PROTAC: a small molecule that binds it is known.
Target class: Secreted protein
Chemical probes: Luteoloside
Gene: Protein-coding gene on chromosome 4 (122,451,470 to 122,456,725, reverse strand). Ensembl gene ENSG00000109471.
Subcellular location: Secreted
Pathways (Reactome):
Immune System: Interleukin receptor SHC signaling; Interleukin-2 signaling
Gene expression (Transcription): RUNX1 and FOXP3 control the development of regulatory T lymphocytes (Tregs)
Signal Transduction: RAF/MAP kinase cascade
Gene Ontology:
Molecular function: cytokine activity; interleukin-2 receptor binding; protein binding; growth factor activity; kinase activator activity; carbohydrate binding; glycosphingolipid binding; kappa-type opioid receptor binding
Biological process: cell surface receptor signaling pathway via STAT; interleukin-2-mediated signaling pathway; leukocyte activation involved in immune response; negative regulation of B cell apoptotic process; positive regulation of activated T cell proliferation; positive regulation of B cell proliferation; positive regulation of immunoglobulin production; positive regulation of interleukin-17 production; positive regulation of plasma cell differentiation; cell adhesion; cell surface receptor signaling pathway via JAK-STAT; cell-cell signaling; immune response; natural killer cell activation; negative regulation of apoptotic process; positive regulation of cell growth; positive regulation of cell population proliferation; positive regulation of inflammatory response; positive regulation of leukocyte differentiation; positive regulation of leukocyte proliferation; positive regulation of tissue remodeling; T cell differentiation; G protein-coupled receptor signaling pathway; negative regulation of T-helper 17 cell differentiation; phospholipase C-activating G protein-coupled receptor signaling pathway; and 8 more
Cellular component: extracellular region; interleukin-2 receptor complex
Genetic constraint (gnomAD): Loss-of-function variants: 1 observed, 7.36 expected, observed/expected ratio (o/e) 0.14, 90% interval 0.047 to 0.64. That is too few expected variants to judge how well the gene tolerates losing a copy. Missense variants: 66 observed, 97.14 expected, observed/expected ratio (o/e) 0.68, 90% interval 0.56 to 0.83. Synonymous variants: 39 observed, 37.94 expected, observed/expected ratio (o/e) 1.03, 90% interval 0.8 to 1.34.
Homologues: Orthologues: chimpanzee IL2 (100% identical), macaque IL2 (98% identical), rabbit IL2 (79% identical), dog IL2 (75% identical), pig IL2 (72% identical), rat Il2 (66% identical), mouse Il2 (63% identical), guinea pig IL2 (62% identical).
Diseases named in the same sentence as IL2 in open-access papers:
IL2 is named in the same sentence as 1,027 diseases in open-access papers, as found by Europe PMC text mining. Sharing a sentence is not in itself a finding about the gene and the disease. The quoted sentences say what the papers report.
melanoma (870 papers, 1983 to 2026). A malignant, usually aggressive tumor composed of atypical, neoplastic melanocytes. "High-dose interleukin-2 (IL-2) used in renal cell carcinoma and melanoma is associated with fluid accumulation in extravascular space." (PMID 37261188, 2023). "While high-dose IL-2 therapy has an overall response rate of 15% in melanoma and kidney cancer patients, it can also cause significant systemic toxicity known as vascular leak syndrome." (PMID 37256141, 2023). "Some of the first approved cytokines were interferon α (IFN-α) as an adjuvant treatment for resected high-risk melanoma patients and high-dose IL-2 for metastatic renal cell cancer and melanoma." (PMID 36937769, 2023). "Elevated serum IL-2 levels are associated with significant disease progression in many autoimmune diseases and cancers, including melanoma, autoimmune hepatitis, and systemic lupus erythematosus." (PMID 37883350, 2023). "A clinical trial (NCT01740557) was initiated to evaluate the efficacy of T cells transduced with CXCR2 and with nerve growth factor receptor (NGFR), associated with Recombinant Human IL-2 (Aldesleukin) infusion in melanoma." (PMID 35211124, 2022). "In the pre-ICI era, the gp100 peptide vaccine in addition to IL-2 was associated with a higher response rate and longer progression-free survival compared to IL-2 alone in patients with advanced melanoma." (PMID 35632496, 2022). "A retrospective observational cohort study examining the survival of patients with melanoma and stage 4 renal cell carcinoma linked the occurrence of irAEs after checkpoint inhibitor treatment and IL-2 as a positive prognostic factor for therapeutic response." (PMID 36556267, 2022). "High-dose IL-2 treatment can overcome Treg-associated IL-2 trapping and allow extra IL-2 to activate TILs for treating metastatic renal cell carcinoma and melanoma." (PMID 35104810, 2022). "IL-2-focussed studies build on the previous observation that high-dose IL-2 has single agent activity in melanoma but is associated with significant toxicity." (PMID 36284898, 2021). "Ipilimumab demonstrated induction of IL-2R α-chain expression on the phenotype of NK cells, with subsequent enhanced response to IL-2 stimulation and cytotoxicity, and this was associated with better clinical response in advanced melanoma patients." (PMID 32117298, 2020). "Forty-eight patients with stage III melanoma were treated with Cisplatin, Dacarbazine, and Vinblastine, in association with IL-2 and IFN-alfa." (PMID 32708968, 2020). "Human IL-2 linked to mAbs has been used for phase-I studies for the therapy of melanoma and prostate cancer." (PMID 33299651, 2020). "A higher proportion of patients in the IL-2 monotherapy cohort had melanomas with a BRAF V600E mutation compared with those assigned to SBRT + IL-2 (55% vs 29%, p=0.1)." (PMID 32467299, 2020). "For example, tumor clones from melanoma metastasis split into 2 groups with high and low susceptibility to killing by IL-2 activated lymphocytes." (PMID 31297450, 2019). "Melanoma therapy is mostly immunological, consisting of the administration of interleukin-2 (IL-2), unfortunately associated with toxicity and low response, or interferon-α (IFN-α) which showed some benefits." (PMID 31336922, 2019). "More recently, Lip-MSA-IL-2, a formulation stabilizing IL-2, was associated with the generation of an immune response that prevented melanoma progression in a murine model." (PMID 31114758, 2019). "We have previously reported on the management of acute IL-2 and interferon-related side effects, including interferon-associated depression in the first consensus statement on melanoma." (PMID 29848375, 2018). "Patients with renal cell carcinoma or melanoma who received IT treatment with either recombinant IL-2 or IL-2 encoding plasmids suffered from less toxicity (compared to systemic administration) and promising anti-tumor efficacy was observed." (PMID 30619273, 2018).
melanoma (continued). "Results showed a clear association of IL-2 production with TNFαlo, IFNγlo and TNFαlo, IFNγint producing T cells upon incubation with target melanoma cells." (PMID 28239467, 2017). "Further analysis revealed that melanoma patients had a sub-optimal STAT1 activation response linked to lower IL-2-induced IFN-γ secretion in both CD56hi and CD56low NK cell subsets." (PMID 27153543, 2016). "IL-2 treatment of melanoma is unfortunately associated with severe toxicity and it causes a large decrease in circulating levels of AA." (PMID 26547841, 2015). "Lastly, BREAK-3 was a large multicenter open-label randomized phase III clinical trial that enrolledpatients with previously untreated (other than with interleukin-2) BRAF V600E-mutated stage IV melanoma." (PMID 25089220, 2014). "Further studies in larger cohorts of patients are still needed to determine the safety risk and likelihood of response to HD IL-2 in patients with melanoma brain metastases." (PMID 23762555, 2013). "But considering the confounding factor guarantee-time bias, the association between an improved outcome in melanoma patients receiving IL-2 and autoimmunity was lost." (PMID 23483974, 2013). "Systemic interleukin-2 (IL-2) is an effective immunotherapy for melanoma, but standard doses are associated with severe toxicity." (PMID 27429133, 2013). "DAB/IL2 caused a transient depletion of Treg cells that coincided with the de novo appearance of melanoma antigen-specific CD8+ T cells." (PMID 22165955, 2011). "In the current study, we have found that DAB/IL2 administration to stage IV melanoma patients depletes peripheral blood Treg cells and causes the regression of metastatic tumors in a subset of patients." (PMID 18334033, 2008). "The lack of clinical activity of the anti-CD25 mAb daclizumab given in combination with cancer vaccines to patients with melanoma or ovarian cancer was hypothesized to be linked to the detrimental effects of the IL-2 signaling blockade on cytotoxic Teffs." (PMID 39983024, 2025). "A retrospective analysis of 631 advanced melanoma cases treated with IL-2 alone, IL-2 combined with interferon-α, or IL-2 with chemotherapy across 12 institutions suggested that IL-2 therapy may be associated with long-term survival." (PMID 40647561, 2025). "Notably, high serum IL-2 levels were associated with prolonged survival, underscoring its crucial role in the immune response against melanoma." (PMID 40711287, 2025). "In addition to interleukin-2, there are several other cytokines and chemokines that are associated with melanoma prognosis and progression, including several that have been associated with an improved overall survival." (PMID 38399429, 2024). "Re-engineered IL-2 therapies have been implicated in longer in vivo half-lives, and they target specific receptor conformations, which reduces toxicity among patients with melanoma." (PMID 38399429, 2024). "In a preclinical model of melanoma, miR-155 overexpression in tumor-specific T cells ablated the need for lymphodepletion and may diminish the associated IL-2-associated iRAEs and treatment-related toxicities." (PMID 36248881, 2022). "Treatment with CTLA-4 inhibitors alone or PD-1 inhibitors in combination with intralesional interleukin-2 in melanoma patients may lead to an AEC increase, associated with improved progression-free and overall survival." (PMID 35936009, 2022). "However, the inhibition of melanogenesis increased the susceptibility of melanoma cells to the cytotoxic effect of IL-2-activated immune cells." (PMID 35884783, 2022). "Proinflammatory cytokines have a similar ambiguous role; high-dose interleukin-2 (IL-2) has been used to treat melanoma, whereas TNFα is associated with aggressive breast cancer biology, and its inhibitor, etanercept, is currently tested in the phase II clinical trial for metastatic breast cancer." (PMID 33457427, 2020). "High expression of IL-2 was associated with good clinical outcome in melanoma." (PMID 31462678, 2019).
melanoma (continued). "Eligible patients were HD IL-2 eligible with metastatic BRAF V600 mutated melanoma." (PMID 30053905, 2018). "We hypothesized that a MALDI mass spectrometric signature associated with response to IL-2 in melanoma could stratify outcomes in RCC and that the adverse role of HGF, an apoptotic marker promoting autophagy could be confirmed." (PMID 30400835, 2018). "Lymphodepletion with 5Gy TBI enhances a tripartite ACT treatment consisting of PFI (P = infusion of 1e6 pmel-1 CD8+ T cells, F = vaccination with fowlpox encoding hgp100 and I = high dose IL-2) in mice with B16F10 melanoma to a greater extent than in lymphoreplete mice." (PMID 26885368, 2016). "It has been shown that melanoma cells are susceptible to lysis by IL-2-activated NK cells." (PMID 27563819, 2016). "The consensus panel has recognized several systemic therapies for unresectable stage IV melanoma, including high-dose IL-2, ipilimumab and, in BRAF-mutated tumors, vemurafenib, dabrafenib (BRAF inhibitors) and trametinib (MEK inhibitor), as well as referral for ongoing clinical trials." (PMID 25815245, 2015). "While a number of immunotherapies for melanoma have been associated with significant clinical benefit, including high-dose IL-2 and cytotoxic T lymphocyte antigen 4 (CTLA-4) blockade, clinical response to either of these single agents has been limited to 11-20% of treated patients." (PMID 25992289, 2015). "Both IL-2 and IL-24 are associated with melanoma tumour suppression in humans and it is now possible to study the role of these genes in the opossum model, as well as in the maintenance of transmissible allograft tumours in Tasmanian devil facial tumour disease." (PMID 17094811, 2006). "Furthermore, intratumoral administration of an oncolytic virus encoding TNFα and IL-2 also enhanced anti-PD-1 efficacy in mouse melanoma by improving CD8+ T-cell infiltration, suggesting that delivering high concentrations of TNFα to tumors can enhance the efficacy of immunotherapy." (PMID 38195677, 2024). "Additionally, a 50% overall response rate was observed in cyclophosphamide lymphodepleted stage IV melanoma patients receiving autologous MART-1 (melanoma-associated antigen recognized by T-cells), peptide-pulsed DCs, and ex vivo reactivated tumor-infiltrating lymphocytes plus IL-2 treatment." (PMID 37515069, 2023). "Using electroporation of anti-melanoma TIL with in-vitro-transcribed mRNAs encoding membrane IL-2, IL-12, IL-15, caTLR4, or caCD40, alone or in different combinations, we could demonstrate their additive, and often synergistic effects on key parameters concerning TIL function and survival." (PMID 33488585, 2020). "Interleukin-2 (IL-2), an immunomodulatory cytokine that promotes T cell and natural killer (NK) cell activity has been tested extensively in the clinic in the 1980s and 1990s and induced long-term responses in a small group of melanoma patients, but also caused severe toxicities." (PMID 27160390, 2016). "For example, a study showed that low-dose IL-2 therapy in a patient-derived melanoma organoid model improved the proliferation and functionality of CD4+ and CD8+ T cells, leading to enhanced antitumor responses." (PMID 41484095, 2026). "Engineered Lactobacillus producing IL-2, combined with anti-PD-1 antibody treatment, notably enhanced tumor suppression in melanoma mouse models." (PMID 41355950, 2026). "IL-2 has been used in clinical settings to treat various cancers, including melanoma and renal cell carcinoma." (PMID 41355950, 2026). "Talimogene laherparepvec (T-VEC) and interleukin-2 (IL-2) are both used for the intralesional treatment of melanoma skin metastases." (PMID 40171522, 2025). "The authors showed that IL2-sEVs decreased melanoma sEV production and melanoma-PD-L1 expression, mediated through miR-181a-3p and miR-223-3p." (PMID 40560407, 2025). "The gp100: 209–217(210M) peptide has been tested as a vaccine in combination with IL-2 to improve clinical outcomes in patients with advanced melanoma." (PMID 40746887, 2025).